BRD4 (bromodomain containing 4)
Diseases named in the same sentence as BRD4 in open-access papers (continued):
Sharing a sentence is not in itself a finding about the gene and the disease.
breast cancer (continued). "JQ1 is a targeted inhibitor of the bromodomain protein BRD4 and exerts anticancer effects, especially in breast cancer, by inhibiting the epigenetic modification recognized by BRD4." (PMID 38605023, 2024). "QCA570 also potently induced BRD4 degradation (DC50 ≈ 1 nM) in several breast cancer cell lines at nanomolar concentrations." (PMID 38389844, 2024). "Upon treatment with XH2 for 12 h, the BRD4 proteasomal degradation was observed in 231MFP breast cancer cells." (PMID 38389844, 2024). "Our findings present potential lead compounds for the development of potent anti-breast cancer agents targeting BRD4." (PMID 38099141, 2023). "An earlier study on the bromodomain-containing protein BRD4 has revealed its two bromodomain's role in controlling EMT gene expression in breast cancer." (PMID 38072045, 2023). "This underscores the need to identify novel BRD4 inhibitors with distinct mechanisms of action to broaden their therapeutic applicability in breast cancer treatment." (PMID 38099141, 2023). "Our analysis supports the effectiveness of BRD4 inhibitor in treating cancer, especially breast cancer." (PMID 37685868, 2023). "CircBCBM1, is upregulated in the breast cancer brain metastasis cells and clinical tissue and plasma samples, acting as the sponge of miR-125a to breast cancer brain metastasis via the miR-125a/BRD4 axis." (PMID 38203348, 2023). "Unexpectedly, RCAN1.4 gene expression is driven by super-enhancers in breast cancer cells, and suppression of super-enhancer activity with BRD4 knockdown or BRD4 inhibitor treatment reduces RCAN1.4 tumor suppressor gene expression." (PMID 38135679, 2023). "In breast cancer, BRD4 and the lysine-specific demethylase 1/nucleosome-remodeling and deacetylase complex interact with each other and are colocalized at SEs." (PMID 37501079, 2023). "For selective protein degradation in breast cancer cells, a BRD4 degrader was conjugated to anti-HER2 (trastuzumab) by a different laboratory." (PMID 36770585, 2023). "In breast cancer, the inhibition of BRD4 has shown promising preclinical results, sparking enthusiasm for TNBC treatment." (PMID 37937685, 2023). "A few BRD4 inhibitors are currently in phase I/II clinical trial stages for breast cancer treatment, such as OTX-015, ABBV-075 and I-BET762." (PMID 38099141, 2023). "Trastuzumab-PROTAC conjugate (Ab-PROTAC 3) that spares HER2 negative cells and only target bromodomain-containing protein 4 (BRD4) in HER2 positive breast cancer cell lines." (PMID 37671162, 2023). "For example, circular RNA circBCBM1 is involved in breast cancer brain metastasis via circBCBM1/miR-125a/BRD4 axis." (PMID 38033864, 2023). "The conjugate was internalized, resulting in active PROTAC for BRD4 degradation only in HER2 positive breast cancer cell lines in vitro." (PMID 36770585, 2023). "When they were administered to breast cancer-bearing models, the BRD4 degradation and photodynamic therapy (PDT) cooperatively boosted the apoptosis of cancer cells, thereby achieving efficient tumor regression." (PMID 36839734, 2023). "Collectively, these findings position BRD4 as a promising therapeutic target with the potential to revolutionize breast cancer chemotherapy." (PMID 38099141, 2023). "In estrogen receptor alpha (ERα)-positive breast cancer cells, BRD4 is a master activator of ERα-occupied super-enhancers and the transcription of ERα target genes, such as RET which in turn activates ERα phosphorylation and ERα target gene expression." (PMID 38135679, 2023). "Tumor specific BRD4 depletion via the POLY-PROTAC nanoplatform combined with photodynamic therapy resulted in tumor regression in a mouse xenograft model of MDA-MB-231 breast cancer." (PMID 36499765, 2022). "BRD4 gene expression was shown to have an immunomodulatory function in breast cancer and was positively correlated with the levels of infiltrating B cells, CD8 + T cells, CD4+ T cells, macrophages, neutrophils, and dendritic cells (DCs)." (PMID 36614001, 2022).
breast cancer (continued). "Although BRD4 amplifications are enriched especially in ovarian cancer, they are also relatively frequently observed in (basal) breast cancer." (PMID 36139513, 2022). "Overexpression of BRD4 has been reported in a variety of malignant tumor types, including breast cancer, hematological malignancies, and lung cancer." (PMID 35902869, 2022). "Although SE drugs seem to be promising therapeutics, resistance to BRD4 inhibitor JQ1 has been reported in breast cancer and AML." (PMID 35740532, 2022). "BRD4 was reported to be involved in the development of leukemia, prostate cancer, and breast cancer, as confirmed by BET-inhibitor (BETi) studies." (PMID 36614001, 2022). "Western blot assays validated that all four PROTACs remarkably degraded BRD4 in MDA-MB-231 breast cancer cells in vitro and consequently suppressed downstream c-Myc expression." (PMID 35882867, 2022). "For instance, JQ1, a bromodomain and extra terminal domain (BET) inhibitor, can suppress tumorigenesis in basal-like breast cancer via inhibiting the interaction between acetylated twist and BRD4." (PMID 35216622, 2022). "The expression of BRD4 was increased in breast cancer samples compared with normal controls (p < 0.001)." (PMID 36499487, 2022). "Compared to normal cells, Brd4 is highly expressed in various cancer cells (e.g., breast cancer, esophageal cancer, stomach adenocarcinoma, and lung squamous cell carcinoma) and it can protect cancer cells against PCD." (PMID 36539410, 2022). "The BRD4 inhibitors JQ1 and MS417 improve the growth-suppressive effect mediated by AKTi, and the BRD4/FOXO3a/CDK6 axis passivates AKT inhibition in luminal breast cancer." (PMID 34011395, 2021). "It has been recently reported that BRD4 expression is significantly higher in breast cancer tissues than in normal controls, and defines poor prognosis in breast cancer patients." (PMID 33809005, 2021). "Taken together, these results suggest that combined inhibition of both RAC1 and BRD4 suppresses breast cancer cell growth and clonogenic potential." (PMID 34803511, 2021). "In breast cancer, several BRD4 alterations involved in the different molecular subtypes have been reported to date." (PMID 33809005, 2021). "This is an important observation as the short form of the human BRD4, which lacks 640 amino acids at the 3′ end is oncogenic in breast cancer, whereas the long form acts as a tumor suppressor." (PMID 34344445, 2021). "In triple negative breast cancer, BRD4 can also promote breast cancer migration and invasion by regulating Jagged1 and Notch1 signaling expression." (PMID 34834420, 2021). "RAC1 and BRD4 showed high expression in different molecular subtypes of breast cancer and high expression of both proteins correlated with decrease survival of breast cancer patients." (PMID 34803511, 2021). "Next, we analyzed the expression pattern of RAC1 and BRD4 in different molecular subtypes of breast cancer." (PMID 34803511, 2021). "Taken together, our study clarified that circBCBM1 accelerated breast cancer brain metastasis via circBCBM1/miR-125a/BRD4 axis, and provided innovative candidate targets for breast cancer brain metastasis diagnosis and therapy." (PMID 34421353, 2021). "BRD4 has been found to play oncogenic roles in many hematological and solid tumors, including melanoma, prostate and breast cancer among others, and has been proposed as a druggable promising target in human cancer." (PMID 33809005, 2021). "It has been reported that Rg3 inhibits cisplatin resistance by repressing PD-L1 lung cancer and the inhibition of BRD4 attenuates PD-L1 expression in breast cancer." (PMID 34111025, 2021).
breast cancer (continued). "Clinically, RAC1 and BRD4 expression positively correlates in breast cancer patient's samples and show high expression patterns across different molecular subtypes of breast cancer." (PMID 34803511, 2021). "Studies in breast cancer have demonstrated a compelling evidence that BRD4 isoforms have distinct and even contradictive functions, providing an insight into mechanisms that are likely at play in other tumor types including ovarian carcinoma." (PMID 34758842, 2021). "TCGA breast cancer samples showed a positive correlation of RAC1 with BRD4 and high expression of both proteins predicted poor prognosis and survival of breast cancer patients." (PMID 34803511, 2021). "We also analyzed the expression levels of both RAC1 and BRD4 in different histological subtypes of breast cancer and nodal status." (PMID 34803511, 2021). "BRD4 inhibition suppresses the expression of Gli1, which is required for transcriptional activation of SNAI1, indicating that BRD4 controls malignancy of breast cancer cells via both transcriptional and post-translational regulation of SNAI1." (PMID 34681726, 2021). "The results indicated that EMC2, G6PD, FLT3, IFNG, ANO6, and SLC1A4 were positively correlated with ferroptosis while CISD1, TP63, and BRD4 were negatively correlated with ferroptosis in breast cancer." (PMID 34222241, 2021). "BRD4 is overexpressed in a variety of parenchymatous tumors, including pancreatic cancer, mammary cancer, and colorectal cancer, and its expression inhibition can hinder the invasion and proliferation of these tumor cells." (PMID 34956562, 2021). "We observed higher expression levels of both RAC1 and BRD4 in different molecular subtypes of breast cancer in comparison to normal-like breast samples." (PMID 34803511, 2021). "A recent paper showed that ZMYND8/RACK7 interacts directly with HIFα and BRD4 to promote transcription elongation of some HIF target genes in breast cancer cells." (PMID 32286255, 2020). "This makes H3K36me3 a potential biomarker, regulated by the super enhancer-mediated BRD4 to study tumor transformation, tumorigenesis, and metastasis in breast cancer as well as in other cancers." (PMID 32412527, 2020). "It has been reported that BRD4 cooperates with twist to mediate twist‐dependent transcription programs in breast cancer tumorigenesis." (PMID 32175692, 2020). "Next, we investigated how flavopiridol and dinaciclib lead to preferential loss of BRD4/NSD3, impacting the oncogene MYC, thereby, promoting cell cycle arrest in breast cancer." (PMID 32412527, 2020). "BRD4 inhibition also suppresses the expression of Gli1 which is required for transcriptional activation of Snail, indicating that BRD4 controls malignancy of breast cancer cells via both transcriptional and post-translational regulation of Snail." (PMID 33343366, 2020). "Previous reports have shown that FL-411, a small-molecule inhibitor of BRD4, can induce BRD4-AMPK-modulated autophagy/autophagic cell death in breast cancer." (PMID 32724459, 2020). "Similar to breast cancer and T‐cell acute lymphoblastic leukemia, the regulation of the Notch1 pathway by targeting BRD4 suggests an epigenetic mechanism." (PMID 33135348, 2020). "Specifically, we identified Brd4 as a key upstream regulator in our dataset, which correlates with an extensive body of literature describing Brd4 as a regulator of the oestrogen response genes in both endometrial and breast cancer." (PMID 32927694, 2020). "KLHDC7B was shown to influence the breast cancer proliferation, BRD4 was reported to influence the immune cell infiltration in breast cancer and promote the cMYC downstream genes’ transcription." (PMID 32500914, 2020). "BRD4 recruits a histone methyltransferase to target genes in ER-positive cells, thus constitutively activating estrogen signaling, a critical pathway in breast cancer tumorigenesis." (PMID 30906568, 2019).
breast cancer (continued). "In the I-Kappa B kinase signaling pathway, our method found genes 4792 (NFKBIA), 23,476 (BRD4), and 79,155 (TNIP2) to be significantly associated with breast cancer survival." (PMID 31874600, 2019). "BRD4 has most often been associated with MYC expression, with this regulation seen in multiple myeloma, AML and ER+ breast cancer." (PMID 31652979, 2019). "Similar to a previous study in breast cancer, the short isoform of BRD4 appeared to have more potent transforming activity than the long isoform of BRD4." (PMID 30036377, 2018). "The CDK6 induction by FOXO3a/BRD4 is responsible for tumor cell survival because overexpression of CDK6 in luminal breast cancer cells significantly relieves AKTi-induced cell growth arrest and apoptosis." (PMID 30518851, 2018). "Here our study discovered the novel role of FOXO3a/BRD4/CDK6 axis in AKTi resistance of luminal breast cancer cells." (PMID 30518851, 2018). "A recent study demonstrated that BRD4 was the upstream regulator of Jagged1 expression and Notch1 signaling, and played an important role in sustaining breast cancer migration and invasion." (PMID 30029633, 2018). "Our recent study also demonstrates that BET inhibitors disrupt the Twist/BRD4 interaction and effectively inhibit invasion and cancer stem cell-like property of basal-like breast cancer (BLBC) cells." (PMID 30518851, 2018). "Here, the authors demonstrate that BRD4/FOXO3a axis upregulates CDK6 promoter activity to promote resistance to AKT inhibition in breast cancer cells and that blocking the action of CDK6 re-sensitizes resistant cancer cells to growth inhibition." (PMID 30518851, 2018). "Recent studies demonstrated that bromodomain-containing protein-4 (BRD4) plays an important role in promoting estrogen-regulated transcription of ER-positive breast cancer cells." (PMID 28055972, 2017). "The Twist-BRD4-WNT5a axis is crucial for the tumorigenicity of basal-like breast cancer both in vitro and in vivo." (PMID 28099910, 2017). "In summary we demonstrate that HOXA9 expression is activated by binding of BRD4 to the CpG hypomethylated HOXA9 promoter in the Claudin-low breast cancer cells attached to ECM." (PMID 27409175, 2016). "Surprisingly, many of the luminal/HER2+ breast cancer cell lines that were sensitive to BRD4 knockdown were subsequently found to be resistant to JQ1 treatment, suggesting that BRD4 also has a bromodomain-independent role in this cell type." (PMID 27283767, 2016). "Using a whole-genome shRNA screen of 77 breast cancer cell lines to identify cancer drivers, BRD4 was identified as a potential target in luminal breast cancer." (PMID 27283767, 2016). "Genome-wide shRNA “dropout screens” for functional genomic analyses on 77 breast cancer cell lines show that BRD4 is preferentially essential for cell viability in luminal/HER2 lines." (PMID 27827996, 2016). "Our previous studies established an important role of bromodomain-containing protein-4 (BRD4) in promoting estrogen-regulated transcription and proliferation of ER+ breast cancer cells." (PMID 25788266, 2015). "A number of studies have uncovered an essential role for BRD4 in various malignancies including Myc-driven cancers, leukemia, lymphoma, lung adenocarcinoma, prostate and breast cancers." (PMID 25788266, 2015). "While other groups provided the evidences that the two isoforms of BRD4 (short isoform and long isoform) share the same N-terminal region except for the final three amino acids and have opposing roles in breast cancer growth and progression." (PMID 25603177, 2015). "This opens up a possibility of significant H4K12ac occupancy in tamoxifen-resistant breast cancers bringing up the therapeutic importance of H4K12ac and combined therapies with BRD4 inhibition and antiestrogens in these cancers." (PMID 25788266, 2015).
breast cancer (continued). "We subsequently demonstrated that increased expression of Brd4 in orthotopic transplant models of mammary tumor significantly suppressed primary tumor growth and metastatic disease." (PMID 24260471, 2013). "More recently we showed that the two isoforms of BRD4, which share the same N-terminal region except for the final three amino acids, have opposing roles in breast cancer growth and progression." (PMID 24260471, 2013). "Due to the known roles of RRP1B in breast cancer progression and metastasis, further efforts were focused on validating its interaction with BRD4-SF." (PMID 24260471, 2013). "We found that the Brd4 longer isoform signature matches low-grade G1 breast cancer tumors while the shorter isoform matches high-grade G3 tumors." (PMID 22295248, 2012). "We have found that the Brd4 long isoform induces a gene expression signature that predicts good outcome in human breast cancer datasets." (PMID 22295248, 2012). "In conclusion, the GRh2-functionalized liposomal platform developed in this study provided a promising strategy for effective BRD4-PROTAC delivery in breast cancer treatment, addressing critical challenges in current targeted therapies through its multifunctional design." (PMID 41567737, 2026). "Also, BRD4 is a well‐known transcriptional regulator that plays a critical role in promoting breast cancer cell proliferation, survival, malignancy, and migration." (PMID 40231553, 2025). "This is supported by a recent report which indicates that even when the bromodomain of BRD4 is inhibited, its interaction with transcriptional co-activators in breast cancer is unimpeded due to the presence of a longer isoform capable of maintaining protein-protein interactions." (PMID 40153395, 2025). "Consequently, BRD4 methylation affects the recruitment of the E2F1 TF to genes involved in mRNA translation in breast cancer cells." (PMID 40809945, 2025). "In addition, LSD1 interacts with BRD4 and colocalizes with this epigenetic regulator at super-enhancers in breast cancer and prostate cancer." (PMID 39501082, 2024). "BRD4 regulates the malignancy of breast cancer cells and is upregulated in breast cancer cells." (PMID 39323672, 2024). "In addition, the two BRD4 isoforms have antagonistic roles in tumour progression and metastasis in breast cancer where BRD4-S functions as an oncogene, while BRD4-L acts as a tumour suppressor." (PMID 38191874, 2024). "Furthermore, BRD4 has been shown to upregulate PD-L1, aiding breast cancer cells in evading immune surveillance." (PMID 38099141, 2023). "Dual-target BRD4 inhibitors have exhibited synergistic effects in breast cancer therapy." (PMID 38099141, 2023). "BRD4 therefore induces breast cancer cell proliferation and tumor progression." (PMID 38135679, 2023). "The super-enhancer “reader” BRD4 forms a protein complex with the repressive LSD1/NuRD transcription regulators at super-enhancers to suppress the expression of drug resistance genes in breast cancer cells." (PMID 38135679, 2023). "Interestingly, after the first demonstration that BET family proteins, especially BRD4, affect self-renewal and tumorigenicity of breast cancer stem cells via the Notch signaling pathway, an analog mechanism was also observed in GSCs." (PMID 36982740, 2023). "Since the introduction of JQ1 by Mitsubishi in 2010 as the first efficient BRD4 inhibitor, both academic and industrial sectors have dedicated significant efforts to develop an array of BRD4 inhibitors for breast cancer treatment, with a particular focus on triple-negative breast cancer (TNBC)." (PMID 38099141, 2023). "FOXO3A dephosphorylation, nuclear and cellular translocation, and the disruption of its interaction with SirT6 are brought on by the protracted therapy of luminal breast cancer cells with AKT inhibitors, which also causes FOXO3A acetylation coupled with BRD4 recognition." (PMID 37626655, 2023).